HTT (huntingtin)
Diseases named in the same sentence as HTT in open-access papers (continued):
Sharing a sentence is not in itself a finding about the gene and the disease.
Huntington disease (continued). "Huntington disease (HD) is caused by expansion of a cytosine-adenine-guanine (CAG) trinucleotide repeat in the 5'-translated region of the IT15 gene on chromosome 4, which encode the protein huntingtin." (PMID 16372906, 2005). "We demonstrate the new experiment by characterizing, for the first time, pico- to nanosecond dynamics along a 16-residue polyglutamine stretch within the protein huntingtin, the causal agent of Huntington's disease, as well as millisecond conformational exchange in the SH3GL3 protein." (PMID 41703747, 2026). "In Huntington’s disease (HD), alternative splicing alteration emerged as a molecular mechanism in view of individually reported mis-splicing events in neurodegeneration-linked genes such as HTT itself, MAPT and TAF1." (PMID 41928095, 2026). "Additionally, increased HSPB8 expression prevents aggregation of the mutant huntingtin protein (Htt43Q), a pathogenic factor in Huntington’s disease." (PMID 40385290, 2025). "The dual-adaptor protein huntingtin is mutated in Huntington’s disease." (PMID 40589526, 2025). "Huntington's disease (HD) is an autosomal dominant, universally fatal hereditary neurodegenerative disorder characterized primarily by selective neuronal loss in the striatum and cortex caused by the mutant huntingtin (mHTT) protein." (PMID 39779371, 2025). "BackgroundThe HTT protein, mutated in Huntington's disease, is expressed throughout the body, and loss of HTT function as an autophagic scaffold may affect tissues and cellular processes." (PMID 41160506, 2025). "To address this, we performed detailed characterization of two well-known triplet repeat loci: the CGG repeat in the 5' untranslated region (UTR) of FMR1, associated with Fragile X syndrome (FXS), and the CAG repeat in the coding region of HTT, associated with Huntington’s disease." (PMID 41256123, 2025). "The extent to which macroautophagy is upregulated to cope with reduced CMA found with HTT KO may be tissue specific, which may relate to the selectivity of tissue pathogenesis observed in Huntington's disease where loss of normal HTT function may be involved." (PMID 41160506, 2025). "Huntington’s disease is an effect of mutation in the gene HTT that encodes the protein huntingtin." (PMID 39859258, 2025). "HTT, the causal gene for Huntington’s disease (HD), is ubiquitously expressed and involved in diverse cellular processes including signaling, transcriptional regulation, cell division, endocytosis, autophagy, and axonal transport, and is required for healthy neurodevelopment." (PMID 41001472, 2025). "Huntington's disease (HD) is a progressive, autosomal dominant neurodegenerative disorder caused by expanded Cytosine-Adenine-GuanineCAG repeats in the huntingtin (HTT) gene, leading to the production and accumulation of mutant huntingtin protein and subsequent neuronal dysfunction and loss." (PMID 41497150, 2025). "Huntington’s disease (HD) is a severe neurodegenerative condition caused by the expansion mutation of the glutamine-encoding Cytosine-Adenine-Guanine (CAG) trinucleotide in exon 1 of the Huntingtin gene (HTT)." (PMID 40283130, 2025). "Growing body of evidence suggests that decreased activity of HIP14 and HIP14L palmitoyl transferases caused by accumulation of mutant Huntingtin and the subsequent alterations in protein palmitoylation play a critical role in the onset of Huntington’s disease (HD)." (PMID 41474785, 2025). "Huntington disease (HD) is a genetic neurodegenerative disease caused by the abnormal expansion of the CAG repeats encoding polyglutamine in the HTT gene resulting in the mutant huntingtin protein." (PMID 38341417, 2024). "Huntington’s disease (HD) is a proteinopathogenic neurodegenerative disorder caused by the abnormal expansion of CAG repeats beyond 36 in exon 1 of the IT15 gene, which encodes the huntingtin (HTT) protein with an expanded polyglutamine (polyQ) in its N-terminus." (PMID 39519337, 2024).
Huntington disease (continued). "Huntington's disease (HD) is a progressive neurodegenerative disorder marked by the gradual decline in physical, cognitive, and mental functions, with aging exacerbating the pathogenic effects of mutant huntingtin (mHTT) protein aggregation." (PMID 39428700, 2024). "Also known as Huntington's chorea, Huntington's disease (HD) is a neurodegenerative hereditary disease that affects the brain and is caused by a mutation on the chromosome 4 Huntingtin (HTT) gene." (PMID 39544557, 2024). "Abnormalities of Hdh due to glutamine chain extension in Huntington’s disease were reported using a battlefield somatic cell line established from Hdh (Q111) knock–in embryos; Hdh (Q111) showed a phenotype distinct from huntingtin loss and overexpression, similar to the full–length mutant protein." (PMID 38525704, 2024). "Huntington’s disease is caused by a mutation in the huntingtin gene (HTT), at loci 4p16.3." (PMID 38920997, 2024). "Huntington disease is a dominant hereditary neurodegenerative disease caused by a CAG trinucleotide repeat which encodes tracts of polyglutamines (polyQs) in the gene encoding the Huntingtin (Htt) protein." (PMID 39684306, 2024). "This prompted us to explore whether ITCs could affect the amount of mutant huntingtin (mHtt) aggregates – a major cause of Huntington’s disease." (PMID 39680190, 2024). "The discovery of the association between alleles of Alipo-protein E (APOE) and polymorphisms in Huntingtin (HTT) genes to the development of Alzheimer’s and Huntington’s disease respectively has changed our understanding of the inherited risk of age-related diseases." (PMID 39044748, 2024). "An expanded CAG repeat in the huntingtin gene (HTT) causes Huntington's disease (HD)." (PMID 38869243, 2024). "Indeed, PQBP1 can bind to a number of causative disease proteins, such as mutated huntingtin associated with Huntington’s disease as well as the mutated androgen receptor that is associated with Kennedy’s disease." (PMID 39205314, 2024). "Also in 2004, it was discovered that Huntington's disease is caused by the abnormal expansion of a CAG repeat in the Huntington's disease gene on chromosome 4, which encodes huntingtin (HTT)." (PMID 38241161, 2024). "Interestingly, highly connected nodes included APP (amyloid beta precursor protein) and HTT (huntingtin), commonly associated to Alzheimer’s disease and Huntington’s disease, respectively." (PMID 39119577, 2024). "Huntington’s disease (HD) is a devastating neurodegenerative disease with mid-adulthood onset that is caused by a dominantly inherited CAG expansion in the huntingtin (HTT) gene." (PMID 38654124, 2024). "Huntington disease (HD) is a neurodegenerative disorder caused by a mutation in the HTT gene." (PMID 37992314, 2024). "Huntington's disease (HD) is a fatal neurodegenerative disease caused by a CAG expansion in the huntingtin (HTT) gene leading to a polyglutamine (polyQ) expansion in the widely expressed huntingtin protein (HTT)." (PMID 39526491, 2024). "Huntington’s disease (HD) is aninherited fatal neurodegenerativedisease caused by the aberrant expansion of the CAG triplet repeatsequence within the first exon of the huntingtin gene (IT15)." (PMID 38752226, 2024). "Huntington’s disease (HD) is an autosomal dominant hereditary neurological disorder caused by the expansion of trinucleotide CAG repeats in the gene coding for the protein huntingtin (HTT), which translates as a polyglutamine repeat in the HTT protein." (PMID 38534746, 2024). "Huntington’s disease begins early, before any symptoms have emerged, with transcriptional dysregulation taking place due to mutations of HTT that disrupt transcriptional machinery via interactions with transcription factors and molecular mediators such as CBP (cAMP response element-binding protein)." (PMID 37445986, 2023).
Huntington disease (continued). "Huntington’s disease (HD) is an inherited neurodegenerative disorder caused by a dominant mutation in the first exon of the huntingtin (htt) gene that leads to an expansion of the CAG trinucleotide sequence (longer than 35 repeats), resulting in a protein with a long polyglutamine-Q stretch." (PMID 37274187, 2023). "Huntington’s disease (HD), an autosomal dominant neurodegenerative disease, is caused by the repetition of cytosine, adenine, and guanine trinucleotides on the short arm of chromosome 4p16.3 within the Huntingtin gene." (PMID 38255146, 2023). "The mutation of the Huntingtin gene causes Huntington’s disease." (PMID 36768453, 2023). "Huntington’s disease (HD) is a severe neurodegenerative disorder caused by a dominantly inherited CAG trinucleotide repeat expansion in the huntingtin gene (HTT) on chromosome 4, resulting in progressive motor, psychiatric and cognitive problems that culminate in dementia and death." (PMID 37993517, 2023). "MISCOs might also be used to study Huntington’s disease, particularly the spread of pathogenic huntingtin (HTT) from the striatum and its effect on different neural populations." (PMID 38052989, 2023). "Similarly, mitochondria isolated from the brains of people affected by Huntington's disease are decorated with the aggregation-prone variant of the Huntingtin protein (Htt)." (PMID 37303235, 2023). "For instance, in Huntington’s disease, the mutation-based excessive N-terminal poly-glutamylation of the protein huntingtin (polyG-Htt) is causative of neuronal cell death, which to a substantial degree is due to the disturbed interaction between poly-glutamylated huntingtin and the cytoskeleton." (PMID 37371492, 2023). "Huntington’s disease is one of the most common dominantly inherited neurodegenerative disorders caused by an expansion of a polyglutamine (polyQ) stretch in the N-terminal region of huntingtin (Htt)." (PMID 36983032, 2023). "Huntington’s disease is a neurodegenerative disorder with an autosomal-dominant inheritance caused by an expansion of CAG repeats that leads to an abnormal polyglutamine strand in the huntingtin protein (HTT)." (PMID 37065462, 2023). "Huntington disease (HD) is a neurodegenerative disorder of the central nervous system resulting from a dominantly inherited CAG trinucleotide repeat expansion in exon 1 of the huntingtin (HTT) gene that encodes the Huntingtin protein." (PMID 37168444, 2023). "Huntington disease (Huntington's disease; HD) is a neurodegenerative disorder caused by an autosomal dominant mutation in the HTT gene—an expansion of the trinucleotide repeat located on exon-1 of HTT to 36 or more polyglutamine (CAG) repeats—leading to the production of mutated Huntingtin (mHTT)." (PMID 37806287, 2023). "Huntington’s disease (HD) is a mostly hereditary neurodegenerative illness (autosomal dominant) caused by a mutation in the huntingtin protein, which results in an expanded number of the CAG trinucleotide repeat (i.e., over 28 repeats) within a polyglutamine tract in the molecule." (PMID 37049607, 2023). "Similarly, it was also reported that Nrf2 activation enhances CT-L and C-L activities in a UPS reporter mouse and promotes the degradation of mutant huntingtin protein in Huntington’s disease (HD) derived cells reducing its associated cytotoxicity." (PMID 37287063, 2023). "Many of these diseases are characterized by inflammation, reactive oxygen species (ROS), and aberrant protein aggregation (e.g., α-synuclein in Parkinson’s disease; amyloid β and tau in Alzheimer’s disease; huntingtin in Huntington’s disease), although precise causes remain elusive." (PMID 38115822, 2023). "Huntington’s disease is an autosomal dominant neurodegenerative disease caused by the repetition of cytosine, adenine, and guanine trinucleotides on the short arm of chromosome 4p16.3 within the Huntingtin gene." (PMID 38255146, 2023).
Huntington disease (continued). "Although aggregates of mutant huntingtin appear to be major causes of Huntington’s disease (HD), its role remains unclear." (PMID 37443816, 2023). "Huntington’s disease (HD) is an autosomal dominant neurodegenerative disorder caused by mutations in the huntingtin (HTT) gene and characterized by the initial loss of neurons along the striatum that slowly progresses into other brain regions including the cerebral cortex and hypothalamus." (PMID 37720551, 2023). "Thus, they concluded that mutant huntingtin caused a change in the expression of P-glycoprotein through the NF-kB pathway in brain capillaries in Huntington’s disease patients and altered the availability of P-glycoprotein substrates in the brain." (PMID 35159390, 2022). "It is unknown whether alterations in EEG brain activity caused by Huntington’s disease may be responsive to huntingtin-lowering treatment." (PMID 35774187, 2022). "Huntington’s disease (HD) is a neurodegenerative disorder caused by aggregation of the mutant huntingtin (mHTT) protein encoded from extra tracts of CAG repeats in exon 1 of the HTT gene." (PMID 36209136, 2022). "Moreover, loss of neurons in the cortex and striatum due to expansion of CAG repeats in the huntingtin gene causes chorea, dementia and psychiatric problems in Huntington’s disease (HD)." (PMID 36404989, 2022). "Huntington’s disease (HD) is caused by a CAG repeat mutation in the huntingtin gene." (PMID 35053088, 2022). "Huntington disease (HD) is a fatal neurodegenerative disorder caused by an expanded polyglutamine tract in the N-terminal region of the huntingtin (HTT) protein, which is expressed ubiquitously throughout the body with the highest levels in the brain and testis." (PMID 36497038, 2022). "However, it seems to be secondary—huntingtin (the gene mutated in Huntington’s disease) is involved in iron homeostasis regulation, and mutated huntingtin results in increased expression of iron response proteins, inducing iron overload." (PMID 35911597, 2022). "Then, using a well-established Drosophila melanogaster model for Huntington’s disease, which expresses the mutated form of human huntingtin, a significant improvement in the motor neuronal function in flies fed with MS3 was observed, proving the in vivo efficacy of this aptamer." (PMID 35563194, 2022). "Additionally, mutations in Huntingtin (Htt), a scaffold protein connecting the selective autophagy receptor p62 to LD cargo disrupt LD macroautophagy (lipophagy) and lead to Huntington’s disease." (PMID 35493070, 2022). "Huntington’s disease (HD) is a hereditary autosomal dominant disease caused by expansion of a cytosine-adenine-guanine (CAG) triplet-repeat within the first exon of the Huntingtin (HTT) gene." (PMID 36557263, 2022). "In patients with Huntington’s disease, Huntingtin (HTT) is mutated." (PMID 36016855, 2022). "Similarly, in patients with Huntington's disease, which is caused by a mutation in a single gene, Huntingtin, expansion of a glutamine‐encoding repeat in the first exon leads to Huntingtin (HTT) protein aggregation." (PMID 35988155, 2022). "Huntington's disease is a fatal neurodegenerative disorder caused by an inherited mutation in the huntingtin (HTT) gene comprising an expanded cytosine-adenine-guanine (CAG) trinucleotide repeat sequence that results in a pathogenic huntingtin protein." (PMID 34806402, 2022). "Huntington’s disease (HD) is a rare, monogenic, autosomal dominant neurodegenerative disorder affecting an estimated 5–10 people per 100,000 that is caused by expansion of the polyglutamine (polyQ) region in the huntingtin protein (HTT)." (PMID 36339819, 2022). "Huntington’s disease (HD) is an autosomal dominant neurodegenerative disorder caused by the abnormal expansion of CAG repeats that encodes the polyQ tract at the N- terminus of the huntingtin protein." (PMID 35392168, 2022).
Huntington disease (continued). "Additionally, fragmented mitochondria and DRP1-impaired activity were also observed in postmortem Huntington’s disease (HD) brains and primary neurons from transgenic mice expressing mutated human huntingtin." (PMID 35408993, 2022). "Huntington disease is caused by a CAG repeat expansion in exon 1 of the huntingtin gene (HTT) that is translated into a polyglutamine stretch in the huntingtin protein (HTT)." (PMID 35793238, 2022). "Huntington disease (HD) is an autosomal dominant, neurodegenerative disease caused by a mutation which results in an expanded polyglutamine (Q) tract near the N-terminus in the huntingtin gene." (PMID 36180805, 2022). "Huntington disease (HD) is an inherited neurodegenerative disorder caused by the expansion of CAG repeats that encode a polyglutamine (polyQ) tract in the huntingtin protein (HTT)." (PMID 35664700, 2022). "The widespread expression of transgene in these two brain regions is important for treating Huntington disease (HD), which is caused by polyglutamine repeat expansion in the Huntingtin (HTT) protein and display neurodegeneration that is most severe in the striatum and cortex." (PMID 36762127, 2022). "Huntington's disease (HD) is a neurodegenerative disease (ND) due to a dominant mutation in the huntingtin gene (HTT), leading to the expansion of the glutamine (Q) amino acid repeat tract in the huntingtin protein (HTT) beyond a threshold of 35-40 polyglutamine (polyQ) repeats." (PMID 35645202, 2022). "Huntington’s disease (HD) is an autosomal dominant neurodegenerative disease caused by an expanded CAG repeat sequence in the huntingtin gene which leads to an abnormal expansion of the polyglutamine tract in the N-terminus of the protein huntingtin." (PMID 36158555, 2022). "Perturbation of KP metabolism due to inflammation has long been associated with the pathogenesis of several neurodegenerative disorders, including Huntington’s disease (HD)—which is caused by the expansion of a polyglutamine stretch in the huntingtin (HTT) protein." (PMID 36140394, 2022). "Ras homolog enriched in the striatum (Rhes) is a small GTPase that also functions as a SUMO E3 ligase to enhance SUMOylation of poly‐Q expanded mutant Huntingtin (mHTT), the protein that is the cause of the lethal neurodegenerative disorder Huntington's disease (HD)." (PMID 32538470, 2021). "SNX21 was recently linked to Huntingtin’s trafficking, which could become relevant to further comprehend Huntington’s disease." (PMID 33931804, 2021). "Similarly, huntingtin, the protein implicated in Huntington's disease, can be found co-localized with intracellular tau lesions in Alzheimer's disease and cytoplasmic Pick bodies in Picks disease." (PMID 33539920, 2021). "Although the genetics of Huntington’s disease (HD) is well studied, the exact biological functions of huntingtin remain speculative, and the exact mechanism of pathogenic peptide aggregation remains a controversial topic." (PMID 34201610, 2021). "Moreover, Src has been linked to Huntington’s disease where expression of polyglutamine-expanded huntingtin activates Src and ultimately promotes neuronal death induced by glutamate." (PMID 33741019, 2021). "In the case of Huntington's disease, the cause is mutation to a single gene known as huntingtin." (PMID 33871358, 2021). "The human huntingtin comprises 3142 residues: the CAG repetition at the 5′ end of the coding sequence of the HTT gene is strongly associated with the Huntington disease, generating a protein variant with an increasing number of glutamine residues (Gln, Q) at the N-terminal domain." (PMID 33809039, 2021). "Accordingly, inclusions of polyQ-expanded Huntingtin are associated with Huntington’s disease." (PMID 34831053, 2021). "The polyglutamine expansion of huntingtin (mHTT) causes Huntington disease (HD) and neurodegeneration, but the mechanisms remain unclear." (PMID 33674575, 2021).